IGF2 (insulin like growth factor 2)
Diseases named in the same sentence as IGF2 in open-access papers (continued):
Sharing a sentence is not in itself a finding about the gene and the disease.
medulloblastoma (16 papers, 2010 to 2024). A malignant, invasive embryonal neoplasm arising from the cerebellum. "YAP has been found to promote radioresistance and genomic instability in medulloblastoma through IGF2-mediated Akt activation." (PMID 34359714, 2021). "Collectively, our data support a model of medulloblastoma development inSB-mutagenised Ptch+/- mice which involves disruption of a novel transcriptionfactor network leading to Igf2 upregulation, proliferation of GNPs,and tumour formation." (PMID 24252690, 2013). "Rao et. al. was the first group to report that co-overexpression of Shh and either activated Akt or IGF2 significantly increased the incidence of medulloblastoma." (PMID 20520772, 2010). "Previously, up-regulation of IGF-2 was observed in YAP overexpressed medulloblastomas." (PMID 37081542, 2023). "Interestingly, YAP has been shown to promote radioresistance and genomic instability in medulloblastoma through IGF-2-mediated AKT activation." (PMID 34359714, 2021). "In other studies, when the imprinting status of H19 and insulin-like growth factors 2 (IGF2) were manipulated, the development of brain tumors including meningiomas, medulloblastomas, and gliomas could be altered." (PMID 32434961, 2020). "In medulloblastoma, Igf2 promotes the proliferation of precursor cells and the PZp53 cell line." (PMID 29348887, 2017). "A similar study elicited medulloblastomas in NTVA mice inoculated with RCAS Shh, Gli, IGF2, N‐myc, or N‐myc T50A." (PMID 39324445, 2024). "A follow‐up study utilised IGF2 signalling and Akt (Akt‐Myr‐D11‐60) activation, creating medulloblastoma with approximately 50% incidence when combining RCAS Shh and IGF2 or Shh and IGF2, in NTVA mice in a Ptc wild‐type background." (PMID 39324445, 2024). "Moreover, in medulloblastoma, heterogeneous inactivation of the PRC2 complex results in a subpopulation of cells that are less fit, but secrete IGF2 that enhances overall tumor growth." (PMID 37418588, 2024).
cervical carcinoma (15 papers, 2005 to 2024). A carcinoma arising from either the exocervical squamous epithelium or the endocervical glandular epithelium. "In cervical cancer, a sole study has found a high frequency of both loss of heterozygosity and loss of imprinting for H19 and IGF2 genes, suggesting that they participate in the molecular pathogenesis of cervical cancer." (PMID 16248899, 2005). "A previous study on cervical carcinoma found similar uncoupling of H19 and IGF2 expression along with biallelic hypomethylation of H19." (PMID 37371750, 2023). "Immunocytochemical analyses showed that IGF-2 bound to IGF2R on cervical cancer cells and other cancer cells, as previously reported." (PMID 31748500, 2019). "To determine the functional significance of the association between DMR methylation at regulatory sequences of IGF2, we computed correlation coefficients for DNA methylation and log-IGF2 gene expression from cervical cancer biopsies." (PMID 23775149, 2014). "Two previous studies examined the expression of H19 and IGF2 genes in samples from cervical cancer patients." (PMID 23984081, 2013). "Another study looking at the relationship between LOI and promoter usage in cervical carcinoma found an exclusive usage of p1 in tumor tissues with underlying IGF2 LOI but not in those tumors with maintenance of IGF2 imprinting (MOI)." (PMID 37371750, 2023). "However, the present data suggest that decreased methylation at the IGF2 regulatory region upregulates IGF2 expression in cervical cancer tissue." (PMID 23775149, 2014). "Albeit IGF2 DMR aberrant methylation has been linked with other cancers, this is the first time that IGF2 intron 3 methylation has been examined in relation to cervical cancer." (PMID 23775149, 2014). "A PPIN of 90 genes identified FLT1, IGF2, IRS1, JUN, KDR, ZEB1, TIMP2 (downregulated), and EZH2, SOX2, and MYB (upregulated) in cervical cancer samples when compared with normal samples." (PMID 36879084, 2023). "It is possible that aberrant methylation in some CpGs in the IGF2/H19 imprinted domain such as the intron 3 CTCF site may be influencing loss of imprinting and the exclusive usage of IGF2 promoter 1, inducing IGF2 overexpression, as has been previously shown in cervical carcinomas." (PMID 23775149, 2014). "From the genes differentially expressed between early and advanced stages of cervical cancer, six genes – three upregulated (BCL3, IGF2, and PIK3R1) and three downregulated (PTPN4, PERP, and DUSP1) were selected for validation by qRT-PCR." (PMID 24403257, 2013). "Other studies have reported elevated IGF2 levels among women with cervical cancer and high- but not low-grade squamous intraepithelial lesions when compared with women with no history of abnormal Pap tests." (PMID 23775149, 2014).
schizophrenia (14 papers, 2005 to 2025). A major psychotic disorder characterized by abnormalities in the perception or expression of reality. "Recent reports have suggested that IGF-2 signaling is linked to schizophrenia." (PMID 32191705, 2020). "In keeping with this, the hippocampal expression of IGF2 was found to rescue adult neurogenesis and improve spatial working memory deficits in the Dgcr8 (DiGeorge syndrome chromosomal region 8) deficient mouse model of schizophrenia (Ouchiet al, 2013)." (PMID 25100745, 2014). "Several schizophrenia-associated genes were down-regulated in the hippocampus of Dgcr8+/- mice, including the insulin-like growth factor 2 (IGF2), which was recently found to play a crucial role in hippocampal functions such as memory consolidation and fear extinction." (PMID 24367288, 2013). "Therefore, we postulate that decreased IGF-2 in schizophrenia might cause structural alterations and dopamine dysfunction in the cortex and striatum to aggravate the negative symptoms." (PMID 32191705, 2020). "In addition, IGF-2 protein was downregulated in the hippocampus of mice lacking DiGeorge chromosome syndrome region 8 (Dgcr8), a candidate gene for 22q11.2 deletion-associated schizophrenia." (PMID 32191705, 2020). "The correlation analyses revealed a crucial positive association of serum IGF-2 levels with the working memory index (r = 0.546, p = 0.001), the attention index (r = 0.405, p = 0.021), and the executive function index (r = 0.606, p < 0.001) in the schizophrenia patients." (PMID 32191705, 2020). "Research has unveiled IGF2’s significant involvement in neurodegenerative diseases, brain injury, schizophrenia, and other pathological conditions through its modulation of ER stress." (PMID 40722704, 2025). "This aligns with the reports of IGF2 downregulation in the dorsolateral prefrontal cortex and lower IGF2 serum levels in schizophrenia patients." (PMID 38516266, 2024). "For example, Igf2 is a target of the transcription factor C/EBPβ that is engaged during memory consolidation in rats, and IGF2 overexpression was shown to rescue working memory deficits in a schizophrenia mouse model." (PMID 38042807, 2023). "Further metabolic dysregulation was detected as an upregulation in IGFBP6 in schizophrenia and a decrease in IGF2 and IGFBP3/5/7/ALS." (PMID 34741130, 2022). "Nevertheless, although there was an inconsistency, a change in serum IGF-2 content in schizophrenia patients was found in both studies." (PMID 32191705, 2020). "In this study, we found that serum IGF-2 levels were positively correlated with working memory and the executive function of schizophrenia patients." (PMID 32191705, 2020). "Prominent hypomethylation of an enhancer within the IGF-2 gene was observed in isolated neurons from the prefrontal cortex of schizophrenia patients." (PMID 32191705, 2020). "IGF-2 was found to be the top downregulated gene in the prefrontal cortex of schizophrenia patients in a large CommonMind consortium RNA-sequencing study." (PMID 32191705, 2020). "Schizophrenia is linked with abnormal brain neurodevelopment, on which IGF-2 (insulin-like growth factor-2) has a great impact." (PMID 32191705, 2020). "The schizophrenia patients had a much lower content of serum IGF-2, IGFBP-3 and IGFBP-7 than controls." (PMID 32191705, 2020). "Further research using animal experiments is needed to reveal the mechanisms of IGF-2 signaling in schizophrenia." (PMID 32191705, 2020). "Hypomethylation of the IGF2 locus was also observed in an analysis limited to individuals with genetic European ancestry (13 controls, 20 bipolar disorder, 19 schizophrenia; Šidák p < 2 × 10−4 for IGF2 locus)." (PMID 31053723, 2019). "Brain weight is decreased in schizophrenia, which raises an interesting suggestion that increases in schizophrenia associated with prenatal famine exposure may be mediated by changes in DNA methylation at the IGF2 locus, although this will involve much more research." (PMID 29922517, 2018).
schizophrenia (continued). "Interestingly, restoration of IGF2 expression in the hippocampus rescued the observed spatial working memory deficits in Dgcr8+/- mice, suggesting that IGF2 contributes – at least in part – to the learning and spatial working memory deficits that are associated with 22q11.2DS-related schizophrenia." (PMID 24367288, 2013). "Association between IGF2 enhancer hypomethylation in prefrontal cortex neurons and increased tyrosine hydroxylase protein has been established in schizophrenia and bipolar patients, indicating epigenetic regulation of dopamine synthesis through IGF2 methylation." (PMID 38516266, 2024). "However, further studies are still needed to elucidate the mechanisms of IGF-2 in the regulation of cognition in schizophrenia." (PMID 32191705, 2020). "Nevertheless, to understand the mechanism of altered IGF-2 signaling in schizophrenia patients, more studies are necessary, which could not only help to essentially understand schizophrenia but also provide new methods for the treatment of schizophrenia." (PMID 32191705, 2020). "Exogenous IGF-2 could reverse the spatial working memory deficits in Dgcr8(+/-) mice, a neurodevelopmental defect model for schizophrenia, by rescuing the proliferation of adult neural stem cells in the hippocampus." (PMID 32191705, 2020). "Thus, we postulate that the alterations in IGF-2 signaling in schizophrenia patients is more likely to be related to the illness per se, rather than a phenomenon secondary to medication treatment." (PMID 32191705, 2020). "First, although we found close associations between serum IGF-2 and the psychotic and cognitive symptoms in schizophrenia patients, the mechanism through which IGF-2 affects schizophrenia-related behaviors is still unknown." (PMID 32191705, 2020). "Both schizophrenia and bipolar patients were consistently hypomethylated at the IGF2 locus, relative to controls (3–9% probe-level hypomethylation in cases relative to controls in IGF2 region)." (PMID 31053723, 2019). "However, future studies are required to test this hypothesis by measuring IGF-2 levels in drug-naive first-episode schizophrenia patients." (PMID 32191705, 2020). "However, whether a change of IGF-2, IGFBP-3 and IGFBP-7 in patients is caused by schizophrenia itself or other confounding factors, for example, influenced by antipsychotic drugs, is still unknown." (PMID 32191705, 2020). "Insulin-like growth factor 2 (IGF-2) and IGF binding protein 7 (IGFBP-7) have been related to schizophrenia (SZ) due to their implication in neurodevelopment." (PMID 36076984, 2022). "Our paper indicates that there were much lower levels of serum IGF-2, IGFBP-3 and IGFBP-7 in Chinese schizophrenia patients." (PMID 32191705, 2020). "For example, it was shown that schizophrenia patients who are not taking any antipsychotic medication have a decreased serum IGF-2 concentration compared with healthy controls." (PMID 33673334, 2021). "In light of evidence that IGF-2 is a potent neural growth-promoting factor and that adult-onset disorders could trace back to development, the results indicate that IGF-2 signaling might be involved in schizophrenia pathophysiology." (PMID 32191705, 2020). "However, in contrast to our findings, one previous study performed in male Arab subjects demonstrated that serum IGF-2 content was much higher in schizophrenia patients, and no change was found in IGFBP-3 levels." (PMID 32191705, 2020).
solitary fibrous tumor (14 papers, 2011 to 2026). Solitary fibrous tumor (SFT) represents a diverse group of ubiquitous rare spindle cell neoplasms that may be benign or malignant and that most frequently arises from the pleura and peritoneum and rarely from other sites such as head and neck, liver and skeletal muscle. "Overexpression of IGF2 related to LOI and receptor tyrosine kinase genes including DDR1, ERBB2, and FGFR1 have implicated the IGF2-INSR pathway in sphere formation of solitary fibrous tumor (SFT)." (PMID 38812777, 2024). "Solitary fibrous tumor (SFT) is a rare mesenchymal neoplasm that may present with non-islet cell tumor hypoglycemia (NICTH), also referred to as Doege-Potter syndrome, primarily due to aberrant secretion of big-IGF2." (PMID 41858356, 2026). "Solitary fibrous tumor (SFT) is a prototypical mesenchymal neoplasm that induces non-islet cell tumor hypoglycemia (NICTH) due to overproduction of insulin-like growth factor 2 (IGF2)." (PMID 30168002, 2018). "Doege-Potter syndrome occurs when incompletely processed insulin-like growth factor 2 (IGF-2), also known as big IGF-2, is produced by a solitary fibrous tumor (SFT) and results in non-islet cell tumor hypoglycemia (NICTH)." (PMID 38405103, 2024).
adrenocortical tumors (13 papers, 2012 to 2025). "IGF2 overexpression has previously been associated with LOH at the IGF2/H19 locus in adrenocortical tumor samples." (PMID 26400872, 2015). "The molecular mechanism of IGF2 overexpression in adrenocortical tumors is linked with paternal UPD (see the results section for details), resulting in methylation of ICR1 and demethylation of ICR2." (PMID 25089899, 2014). "Structural and functional abnormalities at 11p15 are associated with the malignant phenotype in sporadic adrenocortical tumors and IGF2 expression is dramatically up-regulated in at least 80% of sporadic ACCs, compared with either ACA or normal adrenal tissue." (PMID 24066089, 2013). "At the same time, it is possible that altered DNA methylation and insulin‐like growth factor 2 (IGF2) overexpression are involved in the progression of adrenocortical tumours and the promotion of cell proliferation." (PMID 38475883, 2024). "Specifically, elevated IGF-2 levels and IGF-1R overexpression has been implicated as a common occurrence related to adrenocortical tumors." (PMID 35457158, 2022). "These transient knock-down experiments confirmed the effect of IGF2 knock-down on apoptosis and demonstrate further the anti-apoptotic role of IGF2 in the adrenocortical tumor cell line H295R." (PMID 25089899, 2014). "Therefore, our goal was to extend the understanding of the IGF2 role in ACC evaluating the expression of IGF2 in the adrenocortical tumors and the paracrine effects of IGF2 in the proliferation, viability, invasion, and metabolism of ACC cells." (PMID 31378849, 2019). "Altogether, these observations confirm the active role of IGF2 in adrenocortical tumor growth, but also suggest that other growth promoting pathways may be involved in a subset of ACC with low IGF2 expression, which creates opportunities for the use of other targeted therapies." (PMID 25089899, 2014). "Previous molecular studies in adrenocortical tumors showed peculiar gene expression profiles in ACC as compared to ACA, up-regulation of IGF-2 gene and down-regulation of genes involved in steroidogenesis being the most specific molecular signatures of ACC." (PMID 34066306, 2021). "Data from microarray experiments analyzing the transcriptome of adrenocortical tumors suggest few differences in the expression of IGF pathway members between IGF2-low and IGF2-high carcinoma." (PMID 25089899, 2014). "In conclusion, FFPE tissue is not suitable for determining the IGF2 methylation score in patients with an unclear malignant adrenocortical tumor using the currently used method." (PMID 37509652, 2023). "The assessment of the methylation pattern of insulin-like growth factor 2 (IGF2) regulatory regions in fresh frozen material has shown to be valuable in determining the malignancy of adrenocortical tumors, although this has not been elaborately tested in unclear malignant tumors." (PMID 37509652, 2023).
atherosclerosis (13 papers, 2011 to 2024). A disease characterized by the build-up of fatty material and calcium deposition in the arterial wall resulting in partial or complete occlusion of the arterial lumen. "A recent study in atherosclerosis demonstrated that the overexpression of IGF2 enhances oxidized low-density lipoprotein-induced CD36 expression, resulting in increased lipid accumulation in human THP-1 macrophages." (PMID 37107630, 2023). "Accumulating evidence confirms that IGF-2 can facilitate atherosclerosis by accelerating the proliferation and migration of VSMCs." (PMID 32399056, 2020). "We have confirmed that miR-637 restrains the proliferation and migration of VSMCs by targeting IGF-2 and affects the development of atherosclerosis." (PMID 32399056, 2020). "To verify the impact of miR-637 in a mouse model of atherosclerosis, we determined the expressions of IGF-2 mRNA and protein in the smooth muscle cells of the common carotid artery in the AG-NC, AG, AN-NC and AN groups." (PMID 32399056, 2020). "Our in vitro and in vivo experiments show that miR-637 inhibits the proliferation and migration of VSMCs by downregulating IGF-2, thus affecting the progression of atherosclerosis." (PMID 32399056, 2020). "In addition, Qiao et al38 showed that in macrophages, high miR-210-3p levels inhibit lipid accumulation and NF-κB-mediated inflammation by suppressing IGF2 in atherosclerosis." (PMID 38048807, 2024). "Also, miR-637 targets IGF-2 to decline the proliferation and migration and promote apoptosis of VSMCs, contributing to the treatment of atherosclerosis." (PMID 34790697, 2021). "MiR-637 targeting IGF-2 contributes to atherosclerosis inhibition and could be a potential target for this disease." (PMID 32399056, 2020). "The regulatory mechanism of IGF-2 in atherosclerosis remains poorly understood." (PMID 32399056, 2020). "Importantly, IGF-2 and its signaling receptors are crucial players in atherosclerosis." (PMID 32399056, 2020). "Moreover, the IGF2 gene is reported to play a central role in atherosclerosis in a mouse model." (PMID 21752294, 2011). "We also validated that insulin-like growth factor-2 (IGF-2), a crucial factor in the pathogenesis of atherosclerosis, serves as a target gene for miR-637." (PMID 32399056, 2020). "Overexpression of miR-210-3p by inhibiting the IGF-2/IGF-2R axis could inhibit the expression of CD36 and NF-κB, then led to a reduction in the inflammatory response of macrophages and lipid accumulation in atherosclerosis." (PMID 33768092, 2021).